TBX3 (T-box transcription factor 3)
Description:
Transcriptional repressor involved in developmental processes. Binds to the palindromic T site 5'-TTCACACCTAGGTGTGAA-3' DNA sequence, or a half-site, which are present in the regulatory region of several genes. Probably plays a role in limb pattern formation. Required for mammary placode induction, and maintenance of the mammary buds during development (By similarity). Involved in branching morphogenesis in both developing lungs and adult mammary glands, via negative modulation of target genes; acting redundantly with TBX2 (By similarity). Required, together with TBX2, to maintain cell proliferation in the embryonic lung mesenchyme; perhaps acting downstream of SHH, BMP and TGFbeta signaling (By similarity). Involved in modulating early inner ear development, acting independently of, and also redundantly with, TBX2 in different subregions of the developing ear (By similarity). Acts as a negative regulator of PML function in cellular senescence.
Synonyms: TBX3-ISO; XHL; UMS
Tractability: Small molecule: it has a binding pocket of medium quality. PROTAC: ubiquitination databases record sites on it.
Gene: Protein-coding gene on chromosome 12 (114,670,255 to 114,684,175, reverse strand). Ensembl gene ENSG00000135111.
Subcellular location: Nucleus
Subcellular location (Human Protein Atlas): Nucleoplasm; Cytosol
Pathways (Reactome):
Developmental Biology: Transcriptional and post-translational regulation of MITF-M expression and activity
Gene Ontology:
Molecular function: DNA-binding transcription activator activity, RNA polymerase II-specific; DNA-binding transcription repressor activity, RNA polymerase II-specific; protein binding; RNA polymerase II cis-regulatory region sequence-specific DNA binding; sequence-specific DNA binding; sequence-specific double-stranded DNA binding; DNA-binding transcription factor activity, RNA polymerase II-specific; RNA polymerase II-specific DNA-binding transcription factor binding; DNA-binding transcription factor activity
Biological process: animal organ morphogenesis; anterior/posterior axis specification, embryo; cardiac epithelial to mesenchymal transition; cardiac jelly development; cellular senescence; embryonic digit morphogenesis; embryonic forelimb morphogenesis; endocardial cushion formation; female genitalia development; follicle-stimulating hormone secretion; forelimb morphogenesis; luteinizing hormone secretion; male genitalia development; mammary gland development; mesoderm morphogenesis; negative regulation of apoptotic process; negative regulation of cell proliferation involved in heart morphogenesis; negative regulation of DNA-templated transcription; negative regulation of myoblast differentiation; negative regulation of transcription by RNA polymerase II; positive regulation of cell cycle; positive regulation of cell population proliferation; positive regulation of transcription by RNA polymerase II; sinoatrial node cell development; skeletal system development; and 10 more
Cellular component: nucleoplasm; nucleus; chromatin; cilium
Genetic constraint (gnomAD): Loss-of-function variants: 11 observed, 38.9 expected, observed/expected ratio (o/e) 0.28, 90% interval 0.18 to 0.47. The synonymous counts are far from expectation, so gnomAD's model fits this gene poorly and the ratio says little. Missense variants: 927 observed, 930.05 expected, observed/expected ratio (o/e) 1, 90% interval 0.94 to 1.05. Synonymous variants: 500 observed, 413.61 expected, observed/expected ratio (o/e) 1.21, 90% interval 1.12 to 1.3.
Gene-disease validity (ClinGen):
ClinGen rates the evidence that TBX3 causes each of these diseases.
ulnar-mammary syndrome (autosomal dominant): Definitive. Ulnar-mammary syndrome (UMS) is a rare developmental disorder characterized by ulnar defects, mammary and apocrine gland hypoplasia and genital anomalies.
Cancer hallmarks: suppression of growth (promotes); proliferative signalling (promotes); escaping programmed cell death (promotes); angiogenesis (promotes); invasion and metastasis (suppresses); invasion and metastasis (promotes)
Homologues: Orthologues: chimpanzee TBX3 (99% identical), macaque TBX3 (99% identical), dog TBX3 (97% identical), pig TBX3 (97% identical), rat Tbx3 (94% identical), mouse Tbx3 (94% identical), guinea pig TBX3 (89% identical), tropical clawed frog tbx3 (76% identical), zebrafish tbx3a (72% identical), Drosophila melanogaster ocm (21% identical), Drosophila melanogaster mid (20% identical), Drosophila melanogaster H15 (19% identical), and 8 more. Paralogues in human: TBX2 (49% identical), MGA (23% identical), TBX1 (23% identical), TBX18 (22% identical), TBX5 (22% identical), TBX4 (22% identical), TBX15 (21% identical), TBX20 (20% identical), TBX10 (19% identical), TBX6 (19% identical), TBR1 (19% identical), TBXT (18% identical), and 4 more.
Diseases named in the same sentence as TBX3 in open-access papers:
TBX3 is named in the same sentence as 142 diseases in open-access papers, as found by Europe PMC text mining. Sharing a sentence is not in itself a finding about the gene and the disease. The quoted sentences say what the papers report.
breast carcinoma (77 papers, 2006 to 2025). "For example, TBX3 is highly expressed in mammary tissues, and its overexpression is associated with the occurrence and progression of breast cancer." (PMID 39897553, 2025). "Despite this, there remains a notable gap in understanding the epigenetic modulation of TBX3 and other factors involved in mammary stem cell maintenance, particularly their role in breast cancer susceptibility and progression." (PMID 40001874, 2025). "Accordingly, loss-of-function mutations of TBX3 or low TBX3 expression levels are predictive of poor prognosis in HER2-positive breast cancer patients." (PMID 38081972, 2023). "Our work indicates that high levels of SIRT6 are indicative of poor prognosis and high risk of metastasis in HER2-positive breast cancer and suggests further investigation of TBX3 as a downstream target of SIRT6 and co-marker of poor-prognosis." (PMID 38081972, 2023). "This is particularly true for HER2-amplified breast cancers, in which almost all TBX3 mutations are loss-of function ones (70% truncating and 35% missense)." (PMID 38081972, 2023). "For instance, TBX3, which encodes for the transcription factor T-box 3 (TBX3), was found to be overexpressed in different types of carcinomas, including breast cancer." (PMID 36358654, 2022). "By further profiling transcriptomic data from the TCGA BRCA and the Farmer Breast study 33, we identified an association of higher TBX3 levels in luminal breast cancers, and ER‐ and PR‐positive cancers." (PMID 30697731, 2019). "TBX3 had previously been shown to represses TBX2 expression by directly associating with the TBX2 promoter in a breast cancer cell line, MCF-12A18." (PMID 30979887, 2019). "GATA3 and TBX3 encode transcription factors that are frequently mutated and highly expressed in breast cancer, respectively." (PMID 30323337, 2018). "Our results reveal that one of genotyped SNPs in TBX3 was associated both with breast cancer risk and clinical outcome." (PMID 26920143, 2016). "The enrichment for conserved residues as targets of missense mutations in TBX3 supports the idea that loss of TBX3 T-box function is relevant for breast cancer progression." (PMID 26579496, 2015). "Restricting the analysis to breast cancer revealed also a slight enrichment of missense mutations in TBX3." (PMID 26579496, 2015). "Due to the clustering of these mutations to the T-domain and for statistical reasons, TBX3 was inferred to be a driver gene in breast cancer." (PMID 26579496, 2015). "In recent exome analyses of somatic mutations in breast cancer, several mutations in TBX3 were identified." (PMID 26579496, 2015). "Stephens and colleagues observed full conservation of the TBX3 residues, which were mutated in their collection of breast cancer sequences among orthologous animal Tbx3 proteins." (PMID 26579496, 2015). "While this loss of function is in agreement with the expectations from the statistical analysis of TBX3 mutations in breast cancer it is in apparent contradiction to several previous observations on the role of TBX3 in oncogenesis." (PMID 26579496, 2015). "If breast cancer progression is associated with mutations that cause loss of DNA binding, this should also be reflected in TBX3 missense mutations." (PMID 26579496, 2015). "We, furthermore, analyze the occurrence and distribution of TBX3 mutations in breast cancer in relation to other TBX genes and to other tumors." (PMID 26579496, 2015). "The ability of TOX3 to upregulate a number of genes implicated in breast cancer or mammary gland development, including TBX3, BMP7, and IL17RB, was confirmed by qRT-PCR in transiently transfected cells under estrogen-depleted conditions." (PMID 25632947, 2015). "In breast cancer, the frameshift mutations in TBX3 showed an extreme bias to the N-terminal half of the protein." (PMID 26579496, 2015).
breast carcinoma (continued). "The focus of this work was to study the impact of TBX3 mutations as they were identified in primary breast cancers on the transcriptional properties of the protein." (PMID 26579496, 2015). "Potential targets of the breast cancer susceptibility SNPs that we highlighted in the previous section (rs1292011, rs1391720 and rs1391721) include multiple lincRNAs, Metazoa_SRP and TBX3." (PMID 24920305, 2014). "This would be in line with data from sequencing breast cancer genomes; Tbx3 mutations are found specifically in ER+ breast cancers and these mutations are predicted to result in loss of function." (PMID 25343378, 2014). "Furthermore, TBX3, a c‐Myc downstream target, has been implicated in the expansion of breast cancer stem cells (CSCs) as well as the self‐renewal and stemness of mesenchymal stromal/stem cells, ovarian cancer and PDAC CSCs." (PMID 39632282, 2024). "TBX3 mutations are putative driver mutations in breast cancer and usually lead to loss of function." (PMID 37902422, 2023). "We provided functional evidence that breast cancer risk at 12q24 is driven by the TF, TBX3." (PMID 31910858, 2020). "We then examined a second independent patient cohort of 118 patients with non‐high‐grade (low‐ and intermediate‐grade) DCIS, with or without associated early invasive cancer (stage 0 and stage I), for increased power in evaluation of TBX3 association with invasiveness of low‐grade breast cancers." (PMID 30697731, 2019). "TBX3 has been implicated in oncogenesis in breast cancer and melanoma." (PMID 30979887, 2019). "There was also a trend for conservation of the C-terminal TBX3 breast cancer mutations." (PMID 26579496, 2015). "In breast cancer, TBX3 is the most frequently mutated of all TBX genes (17.6%)." (PMID 26579496, 2015). "It is obvious that in breast cancer, TBX3 has the highest number of mutations of all TBX genes." (PMID 26579496, 2015). "Notably Tbx3 has been implicated in breast cancer, which develops in adult mammary epithelium, but the role of Tbx3 in distinct cell types of the adult mammary gland has not yet been characterized." (PMID 25343378, 2014). "Aberrations in human Tbx3 gene have also been implicated in breast cancer." (PMID 24260306, 2013). "Noteworthy, we found that in breast cancer patients TBX3 has many mutations, the majority of which are truncating and missense mutations classified as likely oncogenic and likely loss-of-function events, suggesting that TBX3 acts as a tumor suppressor in breast cancer." (PMID 38081972, 2023). "The SNP rs2161877 near TBX3 was significantly associated with longevity in women (P = 2.9 × 10−6) but not in men (P = .72), which is consistent with previous findings that TBX3 plays an important role in mammary gland development and breast cancer with a close relationship to estrogen." (PMID 30294719, 2018). "Interestingly, mutations in TBX3 have recently been identified in breast cancers suggesting that misregulation of TBX3 may be important for the genesis and pathobiology of breast cancer." (PMID 25350852, 2014). "Studies have shown that TBX3 can promote the proliferation, migration, and invasion of breast cancer cells through various mechanisms while inhibiting apoptosis." (PMID 39897553, 2025). "Questions such as how specific genes, like TBX3 or components of the WNT and FGF signaling pathways, are epigenetically regulated by maternal nutrition, and their implications for lifelong breast cancer susceptibility, remain underexplored." (PMID 40001874, 2025). "TBX3-overexpressing cancer cells in ERα breast cancer cell lines promote CSCs expansion through paracrine FGF signaling." (PMID 38965548, 2024). "Some studies have revealed that estrogen can stimulate breast cancer stem cell proliferation via the paracrine FGF/FGFR/T-box transcription factor 3 (TBx3) signaling pathway, and inhibiting this pathway curtails cancer stem cell expansion in TNBC." (PMID 38699644, 2024).
breast carcinoma (continued). "In breast cancer cells, miR-206 inhibits the expression of the TBX3 gene by directly binding to it, thereby suppresses the cancer stem cell population." (PMID 38965548, 2024). "Ectopic TBX3 expression enhances the formation of breast cancer tumorspheres, which are generated by the proliferation of individual CSCs." (PMID 38965548, 2024). "This evidence indicates that TBX3 has a tumor suppression function and its loss phenocopies SIRT6 amplification in HER2-positive breast cancer." (PMID 38081972, 2023). "As shown for SIRT6-OE, TBX3 low expression is predictive of poor prognosis specifically in HER2-positive breast cancer patients." (PMID 38081972, 2023). "In silico analyses of gene expression profile datasets identified GLI3 as a putative interacting partner of TBX3, an important regulator in embryonic mammary gland development commonly overexpressed in breast cancer (see also section on TBX below)." (PMID 35846378, 2022). "While, as a transcriptional activator, TBX3 over-expression elevated CXCR2 ligands in breast cancer as well, indicating similar regulatory mechanisms were involved." (PMID 35332119, 2022). "Regarding the role of TBX3 in cancers, the expression of TBX3 has been reported to be enhanced in advanced gastric cancers and breast cancers and contributed to the progression of these diseases." (PMID 36923312, 2022). "In comparison, c-Jun specifically binds with -371 (here termed as -360) AP-1 site and transactivates TBX3 expression during breast cancer development." (PMID 35332119, 2022). "Most recently, TOPK was shown to positively regulate TBX3 in the TGF‐β/Smad signaling pathway in breast cancer, hence enhancing epithelial–mesenchymal transition (EMT) and tumor cell invasion." (PMID 34115928, 2021). "More recently, TOPK has been shown to positively regulate the TBX3 in TGF‐β/Smad signalling pathway in breast cancer, thereby enhancing epithelial‐mesenchymal transition (EMT) and tumour cell invasion." (PMID 32960500, 2020). "TBX3 is overexpressed in many cancers including breast cancer and contributes to oncogenesis at multiple levels including the promotion of proliferation, tumor formation, and metastasis." (PMID 31910858, 2020). "TBX3 is regarded as a biomarker for breast cancer and has high importance in breast cancer diagnosis and treatment." (PMID 33324444, 2020). "Examination of ICGC data revealed breast cancer (BRCA) as amongst the top TBX3 mRNA expressers across all tumor tissue sites." (PMID 31570773, 2020). "TBX3 is a transcription factor frequently overexpressed in various types of human cancers, especially breast cancer." (PMID 31968594, 2020). "TBX3 also promotes mammary epithelial cell stemness and the initiation and progression of breast cancer." (PMID 33217982, 2020). "Assessing TBX3 by immunohistochemistry in early‐stage (stage 0 and stage I) breast cancers revealed high expression in low‐grade lesions." (PMID 30697731, 2019). "In this study, we explored the role of TBX3 in breast cancer progression pathways, focusing specifically on its involvement in the induction of EMT and the transition from DCIS to invasive carcinoma." (PMID 30697731, 2019). "Collectively, analysis of publicly available data further supports the association and likely involvement of TBX3, along with downstream EMT transcription factors SLUG and TWIST1, in the aggressiveness of low‐grade breast cancers." (PMID 30697731, 2019). "TGFβ1-activated TBX3 protein expression is mediated by Smad3/4 and TBX3 is overexpressed in several cancers, including breast cancer." (PMID 27863437, 2016). "In order to test the effect of TBX3 on breast cancer progression, each TBX3 isoform was overexpressed in the 21NT cell line (representing DCIS)." (PMID 27553211, 2016).